DMBT1 (deleted in malignant brain tumors 1)
Diseases named in the same sentence as DMBT1 in open-access papers (continued):
Sharing a sentence is not in itself a finding about the gene and the disease.
lung carcinoma (8 papers, 2004 to 2021). "Indeed, the alterations found in these genes such as RYR2, NOTCH1 and DMBT1 have strong association with high tumor burden and tumorigenesis, possibly resulting in a worse prognosis in lung cancer patients." (PMID 34336686, 2021). "Remarkably, this resembles the changes of DMBT1 expression and localisation observed in other tumor types originating from mono-layered epithelia such as primary esophageal adeno-carcinomas and lung carcinomas." (PMID 15301691, 2004). "DMBT1 was a candidate tumor suppressor gene; DMBT1 expression is often lost in lung cancer, indicating that DMBT1 inactivation may have a significant influence on lung tumorigenesis." (PMID 27980454, 2016). "Expression analysis reveals that hypoxia induced lung cancer related biomarkers, HIF and its modulating proteins (TGM2, CSNK1A1, CTNNA1, NAMPT/Visfatin, TNFRSF1A, ETS1, SRC-1, FN1, APLP2, DMBT1/SAG, AIB1 and AZIN1) are significantly down regulated." (PMID 23122428, 2012). "Also, DMBT1 is demonstrated involved in many biological progress include angiogenesis binding with VEGF, cell proliferation of lung cancer." (PMID 27637083, 2016). "However, recent evidence has shown that DMBT1 is not a typical tumour suppressor gene because it is up-regulated in normal or inflamed epithelium adjacent to lung carcinomas as well as in some primary lung cancers and glioblastomas." (PMID 15301691, 2004).
gastric cancer (7 papers, 2007 to 2025). A primary or metastatic malignant neoplasm involving the stomach. "Gastric cancer has been linked to deletion in malignant brain tumors 1 protein (DMBT1), triosephosphate isomerase (TPI1), and cyclostatin B (CSTB) Many target molecules, including extracellular RNA, amino acids, proteins, and glycoproteins have been the subject of studies on salivary biomarkers." (PMID 41245374, 2025). "The loss of DMBT1 expression may preferentially take place in well-differentiated gastric carcinoma." (PMID 26911362, 2016). "A well-established example is Helicobacter pylori, a major risk factor for gastric cancer, which contributes to tumorigenesis through chronic inflammation, epigenetic reprogramming, and suppression of tumor suppressor pathways, including those involving DMBT1 and E-cadherin." (PMID 40723277, 2025). "Our analysis identified a range of biomarkers, highlighting three proteins - cystatin-B (CSTB), triosephosphate isomerase (TPI1), and deleted in malignant brain tumors 1 protein (DMBT1) - as particularly accurate for gastric cancer diagnosis." (PMID 39119128, 2024). "However, the combination of CSTB, TPI1, and DMBT1 proteins demonstrated the highest AUC value, indicating superior discriminative capacity between gastric cancer patients and healthy individuals." (PMID 39119128, 2024). "Chromosome 10 harbors the oncogene FGFR2 (10q26) and tumour suppressor genes PTEN/MMAC1 (10q23) and DMBT1 (10q25-q26), both involved in carcinogenesis, which could explain the observation of both gains and losses of chromosomes 10 in gastric carcinomas." (PMID 17908304, 2007). "Functional analyses further reveal that REG3A overexpression inhibits proliferation and induces apoptosis in gastric cancer cell lines, largely through modulation of the PI3K/Akt signaling pathway and upregulation of DMBT1, a known tumor suppressor." (PMID 40723277, 2025).
glioblastoma (7 papers, 2012 to 2023). The most malignant astrocytic tumor (WHO grade IV). "Additional loss of chromosome arm 10q is seen in over 75% of IDH-wild-type glioblastoma and usually spans the PTEN locus at 10q23.31, and in 60% of IDH-mutant glioblastoma cases, the most commonly deleted region being 10q25-qter, encompassing the FGFR2 and DMBT1 loci." (PMID 33853673, 2021).
inflammatory bowel disease (6 papers, 2010 to 2023). A spectrum of small and large bowel inflammatory diseases of unknown etiology. "DMBT-1 is a gene encoding an alternatively spliced protein involved in epithelial regeneration and innate host defense and is significantly upregulated in inflammatory bowel disease." (PMID 35039476, 2022). "In this study, we analyzed the role of DMBT1 single nucleotide polymorphisms (SNPs) regarding inflammatory bowel disease (IBD) susceptibility and examined their functional impact on transcription factor binding and downstream gene expression." (PMID 24223725, 2013). "DGE of the lower villus zone revealed that NEC epithelial cells exhibited substantial increase in the antimicrobial genes LCN2, REG1A, REG1B, and DMBT1, genes previously shown to be elevated in inflamed epithelium associated with inflammatory bowel disease (IBD)." (PMID 37205711, 2023). "Deleted in malignant brain tumours 1 protein (DMBT1) and surfactant protein D (SFTPD) are antimicrobial peptides previously linked to inflammatory bowel disease (IBD) susceptibility." (PMID 34828659, 2021).
prostate carcinoma (5 papers, 2010 to 2021). A carcinoma that arises from epithelial cells of the prostate gland. "Similarly, in prostate cancer, loss of DMBT1 protein expression and low mRNA expression were correlated with advanced clinical disease such as local invasion and bone metastasis." (PMID 33540589, 2021). "The human DMBT1 gene, involved in terminal differentiation of epithelial cells, is located on chromosome 10 q, a region often deleted in prostate cancer and also containing the PTEN tumour suppressor." (PMID 20626841, 2010).
adenoma (4 papers, 2007 to 2024). A neoplasm arising from the epithelium. "Specifically focusing on CDX2++ epithelial cells within high dysplasia regions, we suggest MARCKS, CD99, and DMBT1 as potential indicators for the transition from adenoma to carcinoma." (PMID 39252972, 2024). "Given our observation that CDX2++ cells most directly reflect the progression from adenoma to cancer, we evaluated the relative abundance of candidate proteins MARCKS, CD99, and DMBT1." (PMID 39252972, 2024). "To determine if protein patterns specific to CDX2- stromal and CDX2++ epithelial cells could be replicated using alternative methods, we orthogonally investigated DMBT1, CD99, and MARCKS as potential markers for adenoma stratification." (PMID 39252972, 2024). "Through various independent methods, DMBT1 emerged as a candidate that effectively stratified colorectal adenomas along the adenoma-to-carcinoma axis, irrespective of cell-type enrichment via DVP." (PMID 39252972, 2024). "DMBT1 expression has primarily been observed in cells of the immune system and epithelial linings, driving not only differentiation but also carcinogenesis when absent, which makes it promising candidate for driving adenoma-carcinoma progression." (PMID 39252972, 2024).
melanoma (4 papers, 2012 to 2023). A malignant, usually aggressive tumor composed of atypical, neoplastic melanocytes. "DMBT1 showed significantly low expression in the primary tumors and metastatic tissues of the melanoma patient samples although normal tissue had high expression." (PMID 32983966, 2020). "In addition, DMBT1 had one of the lowest expressions in melanoma TCGA data compared to all other cancers in the TCGA Pan-Cancer Atlas." (PMID 32983966, 2020). "The role of CD271 as mediator of melanoma metastasis is further underpinned by the inverse regulation of the known suppressor of melanoma metastasis KISS138 and DMBT1 (deleted in brain tumors 1)." (PMID 28112719, 2017). "DMBT1 was under-expressed in all melanomas in this study, albeit the decreases were not statistically significant." (PMID 38260202, 2023). "We analyzed a few of the top DEGs (NRP2, CAPN3, DMBT1, BRAF, DDIT3, PPP1R3C, NF1) using The UCSC Xena platform that has large number of RNA-seq data of normal tissue from healthy individuals (GTEx) and primary tumor and metastatic tissue data from melanoma patients (TCGA)." (PMID 32983966, 2020).
COVID-19 (3 papers, 2021 to 2025). A disease caused by infection with severe acute respiratory syndrome coronavirus 2. "We identified four variants associated with COVID-19 severity with genome-wide significance (rs58027632 in KIF19; rs736962 in HTRA1; rs77927946 in DMBT1; and rs115020813 in LINC01283)." (PMID 40149929, 2025). "Compared across different disease types, all diseases, COVID-19 (low viral load), influenza, and ARDS showed enrichment for DMBT1, a gene known to be upregulated and dysregulated in pulmonary injury and fibrosis." (PMID 35233546, 2022).
endometrial cancer (3 papers, 2019 to 2021). Primary or metastatic malignant neoplasm involving the endometrium (mucous membrane that lines the endometrial cavity). "Thus, the finding in our study that COMP and DMBT1 expression is associated with survival in endometrial cancer is supported by previous studies reporting the same for other cancers." (PMID 33540589, 2021).
gallbladder carcinoma (3 papers, 2016 to 2023). "Recently, a reduction in DMBT1 expression has been observed in various cancer types, such as BC, prostate, and gallbladder cancers." (PMID 37762335, 2023). "In the gallbladder cancer, CRNDE acted as a scaffold of DMBT1 and C-IAP1 complexes to activate PI3K-AKT pathway, which subsequently promoted gallbladder carcinoma carcinogenesis." (PMID 29299168, 2017). "Apart from functional role of CRNDE as a competitive endogenous RNA, CRNDE also played the oncogenic role via acting a scaffold of DMBT1 and C-IAP1 complexes to activating PI3K-AKT pathway in gallbladder cancer." (PMID 29299168, 2017).
glioma (3 papers, 2008 to 2024). A benign or malignant brain and spinal cord tumor that arises from glial cells (astrocytes, oligodendrocytes, ependymal cells). "In total 148 genes are located on 10q25.2-qter, including MGMT, DMBT1 and ERCC6, while the usual suspect, PTEN, is located more proximal to the centromere and is preferentially lost in higher grade gliomas." (PMID 25245118, 2014).
lung disease (3 papers, 2007 to 2022). "In conclusion, DMBT1 seems to be a potential biomarker for airway inflammation in CF and CF lung disease." (PMID 35249163, 2022). "Pulmonary expression of Dmbt1 was approximately 6-fold increased mice with CF-like lung disease compared to wild-type littermates (p = 0.0908)." (PMID 35249163, 2022). "To determine Dmbt1 expression in a mouse model of CF-like lung disease we analyzed the lungs of 3 ENaC-transgene and 3 wild-type mice." (PMID 35249163, 2022). "Thus, inhibitors of these DMBT1-mediated effects could represent useful agents to counteract neonatal lung disease, intractable surfactant deficiency and respiratory failure in addition to drugs already used in neonatal intensive care units such as prenatal corticosteroids and surfactant." (PMID 17908325, 2007). "DMBT1 is part of inflammatory processes in CF and may be used as a potential biomarker for CF lung disease and a potential tool to monitor CF progression." (PMID 35249163, 2022). "Additionally, pulmonary expression of Dmbt1 was approximately 6-fold increased in an established transgenic mouse model of CF-like lung disease (ENaC tg) compared to wild-type mice as detected by qRT-PCR." (PMID 35249163, 2022). "Further studies that analyze longitudinal samples of patients with CF along with their clinical data or at least cross-sectional data of patients with predefined, different stages of CF lung disease are needed in order to establish DMBT1 as a biomarker to monitor progression of CF lung disease." (PMID 35249163, 2022). "In conclusion, DMBT1 expression is upregulated in lung tissue of CF patients and of a transgenic mouse model of CF-like lung disease and may be used as a potential biomarker to diagnose and monitor CF lung disease." (PMID 35249163, 2022). "Lung tissue without lung disease served as control and showed only distinct DMBT1 expression as already described in literature." (PMID 35249163, 2022).
asthma (2 papers, 2019 to 2021). "Moreover, the results of KEGG analysis demonstrated that the DMBT1 gene was correlated with immune-related diseases, such as asthma, graft versus host disease, the intestinal immune network for IgA production, pertussis, and systemic lupus erythematosus, and the total ssGSEA enrichment score." (PMID 34422633, 2021).
bladder cancer (2 papers, 2021).
colorectal cancer (2 papers, 1999 to 2021). A primary or metastatic malignant neoplasm that affects the colon or rectum. "Loss of DMBT1 expression was an independent poor prognostic marker for cancer associated death in colorectal cancer patients, and predicted lymph node metastases, distant spread, advanced stage, and high histologic grade." (PMID 33540589, 2021). "Reverse transcriptase polymerase chain reaction (RT-PCR) amplification demonstrated that 23 (53.5%) of 43 oesophageal, 5 (12.5%) of 40 gastric, and 4 (16.7%) of 24 colorectal cancer cases showed an apparent reduction in DMBT1 mRNA in tumour tissues compared with paired normal tissues." (PMID 9888459, 1999).
esophageal carcinoma (2 papers, 1999 to 2021). A primary or metastatic malignant neoplasm involving the esophagus. "We next studied homozygous deletions within the DMBT1 gene in oesophageal cancers by using duplex PCR." (PMID 9888459, 1999).
influenza (2 papers, 2021 to 2022). An acute viral infection of the respiratory tract, occurring in isolated cases, in epidemics, or in pandemics; it is caused by serologically different strains of viruses (influenzaviruses) designated A, B, and C, has a 3-day incubation period, and usually lasts for 3 to 10 days. "DMBT1, also known as gp340, was shown to inhibit influenza A by binding to hemagglutinin on the virus." (PMID 33809063, 2021).
liver disease (2 papers, 2021). "FMO3 protein and its metabolite (TMAO) participate in the TAF–FMO3–TMAO pathway, which could regulate lipid metabolism, while the downregulated mRNA Dmbt1 could encode the DMBT1 protein, which is related to liver injury and repair mechanisms in liver diseases." (PMID 35127549, 2021). "DMBT1 may play an important role in the proliferation of hepatic progenitor cells (HPCs) in HPV-related liver disease, and decreases in DMBT1 may increase the risk of malignant transformation of HPCs." (PMID 33505467, 2021).
metastatic cancer (2 papers, 2015 to 2025). A carcinoma which has spread from the original site of growth to another anatomic site. "The study also provided potential strategies to treat metastatic cancer, as both DMBT1 targeting with a neutralizing antibody and MUC1 inhibition by GO203 effectively suppresses NET formation and liver metastasis." (PMID 40796724, 2025). "Furthermore, a DMBT1 neutralizing antibody was developed with the promise to inhibit tumor–KC interaction and treat metastatic cancer." (PMID 40796724, 2025).
oligodendroglioma (2 papers, 2008 to 2021). A well-differentiated (WHO grade II), diffusely infiltrating neuroglial tumor, typically located in the cerebral hemispheres. "Secondly, its very strong correlation with survival in the grade III oligodendrogliomas group suggests a participation of DMBT1 at the anaplastic stage of gliomagenesis." (PMID 18506188, 2008).
respiratory distress syndrome (2 papers, 2007 to 2022). "Our data showed pulmonary DMBT1 expression in hyaline membranes during respiratory distress syndrome and demonstrated that DMBT1 increases lung surface tension in vitro." (PMID 17908325, 2007). "In analogy to adults, DMBT1 expression is upregulated during inflammatory processes in the newborn lung, for example respiratory distress syndrome where DMBT1 is detected in hyaline membranes and inactivates different surfactant preparations in a dose-dependent manner." (PMID 35249163, 2022). "This raises the possibility that DMBT1 could antagonize surfactant supplementation in respiratory distress syndrome and could represent a candidate target molecule for therapeutic intervention in neonatal lung disease." (PMID 17908325, 2007). "We hypothesized that pulmonary DMBT1 could contribute to respiratory distress syndrome in neonates by modulating surfactant function." (PMID 17908325, 2007). "Pulmonary DMBT1 was localized in hyaline membranes during respiratory distress syndrome." (PMID 17908325, 2007). "DMBT1 expression was found in alveolar epithelial and glandular cells as well as in hyaline membranes of preterm infants with respiratory distress syndrome (RDS) and acute shock lung, and in hyaline membranes of term infants with acute shock lungs." (PMID 17908325, 2007).
Sepsis (2 papers, 2015 to 2022). Sepsis is defined as life-threatening organ dysfunction caused by a dysregulated host response to infection. "The relative VEGF levels were significantly associated with the postnatal age, the earlier determined DMBT1 levels in the tracheal aspirates and with neonatal infection/sepsis." (PMID 25885541, 2015). "An upregulation of DMBT1 has been proven in neonatal gastrointestinal diseases to be associated with inflammation (e.g., necrotizing enterocolitis) and infection in preterm patients (e.g., severe sepsis) independent from gestational age." (PMID 34989914, 2022). "The VEGF levels in the tracheal aspirates of preterm and term infants were significantly correlated with DMBT1 levels (p = 0.0032), the postnatal age (p = 0.0073) and the presence of neonatal infection/sepsis (p = 0.0002)." (PMID 25885541, 2015). "In conclusion, correlation of VEGF levels with postnatal age, infection/sepsis and DMBT1 levels is in good agreement with the findings that DMBT1 levels also correlated with postnatal age and infection/sepsis according to an earlier study." (PMID 25885541, 2015).
viral infections (2 papers, 2012 to 2022). "Lactoferrin, an interaction partner of DMBT1, has functions in the defense against bacterial and viral infections and was found in concentrations up to 3.3 mg/mL." (PMID 23034003, 2012). "The exact mechanism of DMBT1 protein reduction remains unclear, but it is already known that ACC inhibits the synthesis of mucins and different proinflammatory mediators after virus infections in A549 cells." (PMID 35249163, 2022).
age-related macular degeneration (1 paper, 2016). Age-related loss of vision in the central portion of the retina (macula), secondary to retinal degeneration. "We have shown that copy number variation at DMBT1 does not affect risk of developing age-related macular degeneration and can therefore be ruled out from future studies investigating the association of structural variation at 10q26 with AMD." (PMID 27416785, 2016). "We have shown that copy number variation at DMBT1 does not affect risk of developing age-related macular degeneration, and can therefore be ruled out from future studies investigating the nature of association signal at 10q26." (PMID 27416785, 2016).
allergic rhinitis (1 paper, 2022). Inflammation of the nasal mucous membranes caused by an IgE-mediated response to external allergens. "On the contrary, DMBT1 has also been shown to have anti-inflammatory properties in a mouse model of allergic rhinitis, another respiratory disease with marked inflammation." (PMID 35249163, 2022).
alveolar proteinosis (1 paper, 2007). "However, a yield of 0.5 μg DMBT1gp340 per ml BAL from adult patients with alveolar proteinosis has been described and indicates much higher DMBT1-levels in the diseased lung of adults." (PMID 17908325, 2007).